IFI6 (interferon alpha inducible protein 6)
Diseases named in the same sentence as IFI6 in open-access papers (continued):
Sharing a sentence is not in itself a finding about the gene and the disease.
tumor (54 papers, 2015 to 2026). "The results indicate that high expression levels of IFI6 in ESCA are associated with poorer tumor stages and an increased risk of nodal metastasis." (PMID 38473938, 2024). "Many downregulated genes in tumour‐infiltrating peripheral CD8+ T cells are associated with classical IFN responses (IFI6, IFI27, MX1, STAT1, EPSTI1 PARP9, ISG15), cell proliferation (STMN1, CENPF, HELLS, NUSAP1, and DNPH1), and T cell costimulation (CD28, TMIGD2, TNFRSF4, CD27, and TNFRSF18)." (PMID 39350478, 2024). "Specifically, NUCB2, SCGN and IFI6 were markedly upregulated in cells from the tumour centre, whereas COL5A2 was significantly downregulated in this region." (PMID 40913484, 2025). "IFI6 not only aids in cellular survival under drug stress but also promotes aggressive tumor phenotypes, suggesting its viability as a novel biomarker and therapeutic target for overcoming primary TKI resistance." (PMID 40234395, 2025). "As shown in the results, the delay in tumor growth was considerably more pronounced in the combination group than in the single–axitinib–treated group, with reduced expression of IFI6 and GPX4." (PMID 39988631, 2025). "IFI6, an interferon-stimulated gene overexpressed in various cancers, stabilizes mitochondrial function, contributing to apoptosis inhibition and tumor growth." (PMID 39791716, 2024). "Previous studies have shown that IFI6 plays an important role in antiviral, antiapoptotic and tumor-promoting cellular functions, but few studies have focused on the structure or function of avian IFI6." (PMID 38033564, 2023). "Further research has revealed that IFI6 plays an important role in many processes, such as antiviral, antiapoptotic and tumor-promoting activities." (PMID 38033564, 2023). "IFI6 is overexpressed in many cancer types and is involved in stabilizing mitochondrial function, resulting in apoptosis inhibition and tumor growth promotion." (PMID 36338541, 2022). "Of the six genes identified, IFI27, IFI6, IFITM1, ISG15, and BST2 have been reported to be associated with cancer cell proliferation and tumor growth." (PMID 35267998, 2022). "miR-190 is involved in the regulation of several tumor suppressor genes, including CASP1, IFI6, IFITM2 and OAS1, which are associated with the induction of cell apoptosis and interferon response pathways." (PMID 37304648, 2021). "The loss of IFI6 results in E2F2-mediated dysregulation of DNA replication, resulting in cellular senescence or apoptosis and tumor growth inhibition." (PMID 27608486, 2016). "We show that oncogenic NRAS stimulates IFI6 expression to facilitate melanocyte transformation and tumor growth." (PMID 27608486, 2016). "In addition, comparative experiments are needed to explore the interaction mechanism of bacterial presence with immune (CD45 and CD68) or tumor cells (IFI6 and ISG15) based on the existing findings of marker expression correlations." (PMID 38548720, 2024). "For instance, the MeC derived from the largest IC cluster is highly enriched in interferon response genes, such as ISG15, IFI6, LY6E, and MX1, indicating that the underlying interferon response is among the most common source of transcriptional variation shared across tumor samples and cohorts." (PMID 37149682, 2023). "In the present study, all the tumor clusters expressed IFI6 to a similar extent." (PMID 35892844, 2022). "Thus, these xenograft models demonstrated that IFI6 promotes ESCC tumor growth in vivo, and again demonstrated a critical role of IFI6 in mitochondrial Ca2+, OXPHOS efficiency and ATF3/NOX4 axis." (PMID 32727517, 2020). "We next sought to understand how IFI6 controls ROS production and therefore tumor cell viability." (PMID 32727517, 2020). "Notably, tumor growth was significantly inhibited following IFI6 knockdown, whereas upregulation of IFI6 produced the opposite effect." (PMID 32727517, 2020).
tumor (continued). "Future research on the sustained active expression or inhibition of IFI6 and similar downstream molecules associated with HSP90AA1 in EGFR mutant LUAD and other cancer subtypes is also crucial for advancing our understanding of tumor stress responses and resistance." (PMID 40234395, 2025). "Therefore, elevated IFI6 expression could potentially impact the functionality of both B cell receptors (BCRs) and T cell receptors (TCRs), influencing immune surveillance, tumor infiltration, and the overall immune response dynamics." (PMID 38473938, 2024). "While IFI6 overexpression can reverse the DNA replication stress and growth inhibition caused by UBE2T knockdown, it may also promote breast cancer cell growth through non-UBE2T-dependent pathways, influencing the multifaceted tumor phenotype." (PMID 39791716, 2024). "Importantly, immunoblot from tumor tissues demonstrated that the suppression of ATF3/NOX4 axis in IFI6-overexpressed cells while this effect was reversed by phenformin treatment, validating the effect of IFI6-mediated OXPHOS efficiency on ATF3/NOX signaling pathway." (PMID 32727517, 2020). "Tumor cell characterization revealed that Ep3 cells exhibit high expression of interferon‐related genes (IFI27, IFI6) and are involved in antiviral immune responses, cellular stress, immune regulation, and cholesterol homeostasis." (PMID 40552583, 2025). "IFI6, IFI27, OAS1, and OAS3 are part of the interferon-alpha response (IFN-α) pathway, known for its anti-tumor and anti-viral immune responses." (PMID 39809731, 2025). "IFI6 was over-expressed in ESCA and other cancers, impacting patient survival and showing higher expression in tumor tissues than normal tissues." (PMID 38473938, 2024). "The TIMER2.0 database was employed to assess the pan-cancer expression of IFI6, while UALCAN was used to examine its expression across tumor stages and histology subtypes." (PMID 38473938, 2024). "We selected four ISGs, OAS1, ISG15, MX1 and IFI6, for further validation by Taqman Q-RT-PCR in the HCC tumor tissues." (PMID 37686559, 2023). "In this study, we explored and found that highly expressed IFI6 in MSCs promoted the activation of the SDF-1/CXCR4 axis initiation in the TME, which served as a mediator in the stromal component–tumor cell interaction." (PMID 37670388, 2023). "On the other hand, those spots within the tumor parenchyma expressed more tumor cell genes (e.g., PMEL) and IFN-stimulated genes (e.g., ISG15, IFITM3, IFI6), confirming their closeness to tumor cells and IFN activation." (PMID 37655659, 2023). "Several genes of antiviral immune response pathways such as HLA-B, HLA-C, HLA-DQB1 IFI6, IFITM3, CD74, and tumor suppressor genes EFEMP1 and EGR1, are upregulated in tumor and downregulated in TAS." (PMID 34316327, 2021). "IHC was used to validate the abundance of IFI6, ATF3 and NOX4 in tumor tissues derived from xenograft model." (PMID 32727517, 2020). "Similarly, cells in immune_2 and immune_1, which are surrounded by tumor and stroma, respectively, have distinct expression patterns of marker genes such as ISG15, IFI6, and IFI27." (PMID 39960663, 2025). "Macrophage in this cluster had high expression of type I interferon signaling related genes (IFITM3, IFI27, MX1, IFI6, and ISG15) as well as gene features related to immunosuppressive phenotype (APOE, APOC1, S100A9, and GPNMB), whereby participating in tumor immune regulation." (PMID 35265520, 2022). "Of the differentially expressed genes, IFI6, SLC39A9 and ZNF185 showed a strong correlation with tumor progression and patient survival in the OncoLnc database while roles for AKAP12 and DUSP5 in carcinogenesis and poor prognosis have previously been established for other cancer types." (PMID 32849815, 2020). "We found that IFI6 knockdown inhibited the ability of NRASQ61K to transform MEL-ST cells, as shown by the reduced colony formation in soft agar and tumor formation in mice." (PMID 27608486, 2016).
tumor (continued). "Subcutaneous tumor experiments based on the Osimertinib-resistant HCC827-TS cell line revealed that the HSP90 inhibitor AUY922 demonstrated considerable efficacy against Osimertinib-resistant EGFR-mutant LUAD, with IFI6 knockdown showing even greater therapeutic potential in vivo." (PMID 40234395, 2025). "The increased transcripts for EGR1, interferon-induced proteins (IFI6, IFIT1, IFIT3, IFIT5), and MHC class II (HLA-DRA) indicated strong stimulation of IFN signaling, which could result in activation of macrophages in the tumor microenvironment." (PMID 37834191, 2023). "Interestingly, none of these growth inhibitory targets of E2F were upregulated after IFI6 knockdown, which may in part explain why IFI6-mediated upregulation of E2F2 results in dysregulated DNA replication and tumor growth inhibition." (PMID 27608486, 2016). "However, IFI6 knockdown did not affect colony or tumor formation in YUVON cells." (PMID 27608486, 2016). "While IFN-α itself was not differentially expressed in the PD laryngeal SCC, IFI6 and IFI27, two type I IFN-α stimulating genes, showed significantly higher expression in this new tumor." (PMID 36210388, 2022). "The detailed mechanisms of IFI6 and IFI27 regulating tumor growth however have not been well elucidated." (PMID 36210388, 2022).
cancer (40 papers, 2008 to 2025). A tumor composed of atypical neoplastic, often pleomorphic cells that invade other tissues. "For example, editing sites for GALM or IFI6 that led to higher expression were linked to lower survival and more cancer stemness." (PMID 36969056, 2023). "In the in-situ cancer-1 population, we observed region-specific Interferon-induced expressions, such as IFI27, IFI6, which are associated with cancer growth inhibition and apoptosis promotion." (PMID 35835774, 2022). "By utilizing publicly available data from the Gene Expression Omnibus (GEO) and the Cancer Genome Atlas (TCGA), we examined IFI6’s expression level, epigenetic mechanisms, and signaling activities within ESCA." (PMID 38473938, 2024). "For example, GALM (or IFI6) editing sites associated with worse outcomes of LGG patients resulted in higher expression of GALM (or IFI6), and were correlated with higher cancer stemness." (PMID 36969056, 2023). "It is reported that IFI6 is necessary for cancer progression via regulating DNA replication stress, thereby inhibiting cell apoptosis and modulating cisplatin resistance." (PMID 34513825, 2021). "The mRNA expression level of IFI6 is higher in multiple cancers including OC than paired normal samples in GTEx." (PMID 34513825, 2021). "Cancer cell-based experiments demonstrated that the activity of IFI6 controls the growth and survival of ESCC cells through the modulation of cellular ROS production." (PMID 32727517, 2020). "As a new member of the ISG12 family, most research has focused on studying the IFI6 upstream regulatory region or the function of IFI6 in cancer cells." (PMID 26244642, 2015). "IFI6 has been reported to play an essential role in different cancers." (PMID 38473938, 2024). "Furthermore, we explored correlations between IFI6 and various immune cells while also assessing its pan-cancer expression using multiple tools." (PMID 38473938, 2024). "Similarly, we have shown the highly significant impact of high IFI6 expression levels on various types of cancer." (PMID 38473938, 2024). "Hence, during the process of screening the IFI6 gene information, we aimed to gain an overview of the chromosomal distribution of the methylation probes associated with IFI6 and examine the aggregated CpG methylation values in ESCA and other cancers." (PMID 38473938, 2024). "Interestingly, we found that four of the 28 prognostic RESs were associated with higher stemness in corresponding cancers, including RESs of GALM and IFI6 in LGG." (PMID 36969056, 2023). "Notably, HLA-I– cancer cells acquiring a mesenchymal status were associated with enhanced mRNA levels of the IFN-stimulated genes IFIT1, IFIT2, IFIT3, IFI6, IFI27, and CCL2." (PMID 35503263, 2022). "IFI6 may be crucial in mediating apoptosis in many cancers, and it may have antiviral activity against the hepatitis C virus." (PMID 35609018, 2022). "Upregulation of IFI6 may contribute to cancer progression; however, the roles of IFI6 in OC carcinogenesis remain unclear." (PMID 34513825, 2021). "Convincingly, IFI6 is also positive with markers of the NF-κB pathway in cancers." (PMID 34513825, 2021). "Besides PDPN, many of these molecules, such as IFI6, IFI27, IFI44L, and BOP1, also have been reported to be associated with carcinogenesis and treatment in other types of cancers." (PMID 31321241, 2019). "Moreover, its expression is extremely high in multi-drug resistant cancer cells, suggesting that a close correlation between IFI6 levels and resistance to apoptosis." (PMID 26244642, 2015). "IFI6 encodes interferon alpha-inducible protein 6 (also known as G1P3), which has emerged as a pro-survival anti-apoptotic protein based upon studies using cancer cell lines." (PMID 24260178, 2013). "IFI6, also known as IFN alpha inducible protein 6 and G1P3, belongs to the FAM14 family genes and is found to inhibit apoptosis in various cancer systems." (PMID 39070493, 2024).
cancer (continued). "When grouped by ZNF536 expression, we found that in the cancer epithelium, ZNF536 exhibited co-expression with PHOX2B and AR, while being excluded from IFI27, IFI6, and ZFP36." (PMID 38720348, 2024). "XAF1, TRIM31, G0S2 and IFI6 have known roles in apoptosis or its prevention, while PAX7, TRIM31 and PNMA8A are involved in cell development/development of cancer." (PMID 38990812, 2024). "In particular, the expression levels of genes, such as IFI6, MX1, IFIT1, IFIT3, ISG15, OAS1, and OAS2, which belong to the cancer-promoting ISG subset IRDS, were markedly increased." (PMID 35618021, 2022). "Importantly, specific representatives of the residual signature genes (ISG15, IFI27, IFI6, RSAD2) appear to aid cancer cells in evading immunosurveillance and inflammatory cells by inhibiting apoptotic processes." (PMID 40312750, 2025). "Since IFI6 and IFI27 are downstream targets of activating transcription factor-3 and suppressed to mediate its growth inhibitory actions in cancer cells, it is feasible that the same mechanism mediates the growth inhibitory actions of miR193a-3p in spheroids and needs to be investigated." (PMID 36766731, 2023). "Both IFI6 and IFI27 are type I IFNalpha ISGs, and increasing evidence shows that IFNalpha plays dual opposing roles in cancer development based on ISGs, which determine whether it has anti- or pro-tumorigenic functions." (PMID 33539340, 2021). "Further in-depth studies have revealed that high expression of IFI6 in ESCC cells exerts an oncogenic effect and that the knockdown of IFI6 expression increases the accumulation of reactive oxygen species, which leads to inhibition of the proliferation of cancer cells and induction of apoptosis." (PMID 38033564, 2023).
bacterial infection (1 paper, 2021). "In our study, IFI6 was found to be upregulated during bacterial infection." (PMID 34490145, 2021).
IFI6 also shares sentences with these, for which no sentence is quoted: HIV-1 infection (3 papers); lung carcinoma (2); neurodegenerative disease (2); rheumatoid arthritis (2); adenoma (1); AIDS (1); Arthritis (1); atherosclerosis (1); atopic asthma (1); B-cell acute lymphoblastic leukemia (1); bacterial pneumonia (1); bovine respiratory disease complex (1); dengue (1); Diabetes (1); glioblastoma (1); Hepatitis (1); interstitial lung disease (1); measles (1); metastatic disease (1); Moyamoya disease (1); multiple myeloma (1); muscular dystrophy (1); nasopharyngeal carcinoma (1); oligodendroglioma (1); oral squamous cell carcinomas (1); ovarian disease (1); parasite infection (1); psoriatic arthritis (1); renal cell carcinoma (1); respiratory syncytial virus infection (1).
A further 5 diseases each share a sentence with IFI6 in 1 paper.